LEP (leptin)
Diseases named in the same sentence as LEP in open-access papers (continued):
Sharing a sentence is not in itself a finding about the gene and the disease.
Cognitive impairment (continued). "Maternal hyperleptinemia has been suggested to induce leptin withdrawal in the fetal brain, resulting in the downregulation of leptin receptors and leptin signaling leading to cognitive impairment." (PMID 35937892, 2022). "A significant increase in cerebrospinal fluid (CSF) leptin levels was observed in AD patients compared to controls and patients with mild cognitive impairment, suggesting that leptin resistance develops throughout AD." (PMID 36144245, 2022). "This is the first study to evaluate change in cognitive deficits in patients with severe AN, compare differences in cognitive function between AN subtypes, and evaluate leptin as a possible mediator of cognitive impairment in severe malnutrition." (PMID 32760588, 2020). "Leptin resistance and inflammasome activation in the adipose tissue contribute to cognitive deficits, in which neural plasticity is impaired, and neuroinflammatory responses are activated in the hippocampus." (PMID 33379163, 2020). "One of potential scenarios is that higher secretion of leptin is a response to neurostructural alterations of the frontal cortex and related cognitive impairment in FEP." (PMID 32547431, 2020). "On the contrary, mild cognitive impairment was positively correlated with serum leptin and IL-1β levels, and inversely correlated with adiponectin in elderly population." (PMID 29156608, 2017). "Hippocampal-dependent cognitive deficits induced by HFD have been attributed to leptin, calcium dysregulation, inflammation, cellular stress, and impaired insulin signaling." (PMID 27676071, 2016). "Although the exact change of leptin in cognitive impairment population was still inconsistent, many laboratory studies had suggested the neuroprotective effects of leptin against AD." (PMID 26693203, 2015). "Both central leptin resistance and leptin declines share similar pathway of cognitive impairment." (PMID 41516046, 2025). "For instance, trials like NCT00690235, which focused on schizophrenia and medication-induced weight gain, and NCT03560960, which was aimed at Alzheimer’s disease and mild cognitive impairment, highlight the broader implications of improving leptin sensitivity in the context of brain dysfunction." (PMID 39594988, 2024). "It is assumed that the higher concentrations of leptin observed in subjects with higher fat tissue content may be responsible for the protective effect of preventing cognitive disorders." (PMID 38474772, 2024). "Together, these studies suggest that circulating leptin levels may play a role in cognitive impairment." (PMID 38933275, 2024). "Other hormones increased by excess weight gain, such as leptin, appear to have significant roles in neuronal function and morphology, and compromised leptin signaling has been suggested as a key contributor to AD-related pathologies and cognitive impairment." (PMID 38416718, 2024). "Lipid abnormalities may contribute to cognitive impairment in BD through several pathways, and one possible mechanism is to affect the role of leptin." (PMID 38773397, 2024). "As modification of tau and its accumulation at synapses strongly correlates with cognitive impairments in AD, the ability of leptin to limit tau phosphorylation and its targeting to synapses has important implications for the neuroprotective actions of leptin in CNS disorders like AD." (PMID 39000459, 2024). "In line with this neuroprotective role of perinatal leptin, other researchers have recently demonstrated that cognitive impairment in neonatal rat offspring of diet-induced obese dams could be attributed to leptin withdrawal." (PMID 38203399, 2023). "Moreover, the serum leptin level is inversely proportional to the severity of cognitive impairment, indicating that the higher the serum leptin level, the larger the brain volume and the milder the extent of brain atrophy." (PMID 37927863, 2023).
Cognitive impairment (continued). "Moreover, triglycerides can cross the BBB to directly induce hypothalamic leptin and insulin receptor resistance, which contributes to cognitive impairment." (PMID 37086380, 2023). "Similarly, the authors of one study show that plasma leptin levels are lower in subjects with mild cognitive impairment (MCI) or AD compared to control subjects and confirm a decrease in Aß42 and an increase in the tau protein related to MCI and AD." (PMID 35563589, 2022). "In the brain autopsy, CSF leptin levels were significantly higher in AD compared to control and mild cognitive impairment cases, and CSF leptin concentration was correlated with pathological neurofibrillary tangle burden, suggesting that leptin resistance develops during AD progression." (PMID 34795562, 2021). "Impaired leptin signaling is not only believed to be a result of AD pathology, but it may also further promote AD pathology and cognitive deficits." (PMID 32993686, 2020). "Leptin modulates immune response, and hypoleptinaemia can increase the production of pro-inflammatory cytokines that could result in cognitive impairment and delirium." (PMID 30797230, 2019). "Leptin-deficient mice with T2DM show impaired cerebral insulin signaling, thereby leading to the activation of glycogen synthase kinase 3β(GSK3β), the production of Aβ, the hyperphosphorylation of tau protein, and subsequent cognitive impairment." (PMID 31651303, 2019). "Adiponectin, leptin, and IL-1β in elderly diabetic patients with mild cognitive impairment." (PMID 31969813, 2019). "As with insulin, leptin resistance is also associated withimpaired cognition, especially during aging, and impaired leptin function maycontribute to cognitive impairment in MCI in humans." (PMID 29072515, 2017). "Unlike previous scarce data and negative correlation, we also found increased levels of ciliary neurotrophic factor (CNTF) in plasma in several redescriptions describing subjects with high level of cognitive impairment, together with decreased levels of leptin." (PMID 29088293, 2017). "The aim of the study was to determine the serum levels of adiponectin, leptin and IL-1 β in elderly diabetic patients with and without mild cognitive impairment (MCI) and to examine the associations of these markers with clinical and cognitive parameters." (PMID 26432692, 2016). "However, little is known about the relationship between leptin and estrogen in mild cognitive impairment (MCI)." (PMID 26693203, 2015). "Low leptin in four independent studies of Alzheimer’s Disease and in patients with mild cognitive impairment support the suggestion that leptin may be beneficial for age-related cognitive decline." (PMID 28275721, 2014). "Insulin and leptin resistance has been related to the dysregulation of energy balance and to the induction of a chronic inflammatory status which have been recognized as important cofactors in cognitive impairment and AD initiation and progression." (PMID 22701480, 2012). "In that case, the absence of beneficial effects of leptin in the central nervous system would predispose to cognitive impairment." (PMID 22701480, 2012). "In that case, the absence of beneficial effects of leptin in the central nervous system (CNS) would predispose to cognitive impairment." (PMID 21070531, 2010). "Given these irrefutable effects on brain structure and function, it is reasonable to hypothesise that leptin may have roles on mood and cognitive disorders." (PMID 21070531, 2010). "Moreover, treatment with leptin reversed the AD-related cognitive impairments in the AD mouse models, indicating not only that these deficits are leptin-dependent but also that it is feasible that dysfunctions in the leptin system contribute to the development of AD in rodents." (PMID 41462981, 2025).
Cognitive impairment (continued). "Furthermore, circulating leptin levels were significantly reduced in patients with cognitive impairment, which may explain why patients with SCD have increased CA1 gray matter volume and impaired executive function." (PMID 36062154, 2022). "Thus, the current study suggested a complicated relationship among WHR and leptin and cognitive function that alterations in leptin may be involved in the visceral obesity, contributing to cognitive impairment." (PMID 29867443, 2018). "We previously demonstrated that leptin intake during lactation prevents metabolic alterations in the MONW phenotype, including cognitive impairment." (PMID 40944384, 2025). "When cognitive impairment occurs, patients with SCZ seem to have significantly increased Hcy and SHBG and reduced leptin." (PMID 39554652, 2024). "For example, pro-inflammatory factors such as leptin, IL-6, TNF-α which are secreted by adipocytes can cross the BBB and lead to neuroinflammation, which plays a role in cognitive impairment and AD." (PMID 37457589, 2023). "Thus, we hypothesize that neonatal leptin, administered at physiological levels to avoid the potential development of leptin resistance at this critical period, could have a protective role against cognitive impairment induced by fat-rich diets." (PMID 38203399, 2023). "The study found that higher leptin concentrations and a higher leptin/adiponectin ratio were associated with cognitive impairment in the non-obese group only, suggesting that the role of leptin in cognitive impairment with advanced ageing may be limited to non-obese individuals." (PMID 32987813, 2020). "Finally, probably the most important finding of this study was the detection of altered levels of those biological attributes, for subjects with cognitive impairment, that could have potential as therapeutic targets in AD, namely decreased leptin and increased angiopoietin-2 plasma levels." (PMID 29088293, 2017). "Clinically, AD patients had a 7.3 ng/mL lower plasma leptin level on average than non-AD cognitive impairment." (PMID 41516046, 2025). "In a number of studies, plasma leptin levels have also been reported to be lower in individuals with MCI (mild cognitive impairment) or AD compared to normal controls, and negatively correlating with the degree of cognitive impairment and dementia." (PMID 35527735, 2022). "In summary, our results indicate that GMT can alter cognitive deficits and Aβ deposition in ZDF rats, effects that may be achieved through improved insulin resistance and leptin resistance." (PMID 35721013, 2022). "However, a case-control study found that plasma leptin level was not correlated with cognitive impairment and the severity of AD (Ülker and Kenangil 2018)." (PMID 40498212, 2025). "Unraveling these pathways could lead to innovative treatments that specifically enhance leptin signaling within the brain, thereby alleviating cognitive deficits without exacerbating peripheral resistance." (PMID 39594988, 2024). "However, one must recall that leptin can promote inflammatory responses, in-creasing TNF and IL-6, which reduce synaptic plasticity and are related to the progression of AD and severity of cognitive impairment in these patients." (PMID 36674935, 2023). "Several biomarkers were also highlighted as potential biomarkers of GDM-related cognitive impairment such as AGEs, serine-phosphorylated IRS-1 and inflammatory markers such as tumor necrosis factor α (TNF-α), high-sensitivity C-reactive protein (hs-CRP), leptin, interleukin 1β (IL-1β), and IL-6." (PMID 30563117, 2018). "Indeed, cognitive impairment displayed by db/db mice can be improved by normalization of corticosterone levels, without restoring impaired leptin signaling pathway." (PMID 21949705, 2011).
Cognitive impairment (continued). "Additionally, low leptin levels could partially drive cognitive impairment in AD, not only by its action on neuronal growth and function but also by its ability to inhibit amyloidogenic pathways and reduce tau phosphorylation." (PMID 34731089, 2021). "However, it is not yet known whether leptin therapy is able to produce a clinically relevant reduction in cognitive decline in patients diagnosed with mild cognitive impairment or AD." (PMID 34731089, 2021).
Alzheimer disease (92 papers, 2007 to 2026). A progressive, neurodegenerative disease characterized by loss of function and death of nerve cells in several areas of the brain leading to loss of cognitive function such as memory and language. "Are plasma leptin levels associated with baseline and longitudinal changes of the 2 key protein pathologies of Alzheimer disease (AD), amyloid-beta (Aβ) and tau deposition, as measured by positron emission tomography among cognitively normal older adults?" (PMID 38700863, 2024). "This cohort study examines the association of plasma leptin levels with the 2 key protein pathologies of Alzheimer disease, amyloid beta and tau deposition, among cognitively unimpaired older adults." (PMID 38700863, 2024). "Many epidemiologic studies have suggested that low levels of plasma leptin, a major adipokine, are associated with increased risk of Alzheimer disease (AD) dementia and cognitive decline." (PMID 38700863, 2024). "Conversely, not all studies support these findings, in a 15 years longitudinal study showed that higher levels of LEP proteins are associated with reduced incidence of dementia and Alzheimer's disease (AD)." (PMID 35928129, 2022). "Other studies indicated that saturated fatty acid increases plasma leptin in humans, which was associated with the occurrence of Alzheimer’s disease (AD)." (PMID 35739547, 2022). "Most of these have reported an association between lower serum leptin concentrations and higher risk for Alzheimer disease." (PMID 30893833, 2019). "In this review, we are going to discuss the role of the cytokine leptin in brain function and specially in the memory decline associated with Alzheimer’s disease (AD)." (PMID 31191220, 2019). "Transgenic mice that overexpress APP had low leptin levels associated with hypothalamic dysfunction; low leptin levels are linked to Alzheimer’s disease." (PMID 29587359, 2018). "Leptin and Alzheimer’s Disease: Framingham Heart Study data showed a prospective association between high baseline leptin levels and decreased dementia and Alzheimer’s disease later in life." (PMID 29587359, 2018). "As leptin has been linked to Alzheimer's disease, these findings have important implications for understanding of age-related disorders such as Alzheimer's disease." (PMID 29860205, 2018). "Conversely, subjects with lower baseline leptin levels were at increased risk for later Alzheimer’s disease." (PMID 29587359, 2018). "Clinical studies have also identified an association between circulating leptin levels and the risk of certain neurodegenerative disorders such as Alzheimer’s disease (AD)." (PMID 30386207, 2018). "Although it is established that leptin plays a pivotal role in normal brain function, disruption of the leptin system is also linked to neurodegenerative disorders, like Alzheimer's disease." (PMID 23964236, 2013). "The review by Beccano-Kelly summarizes the body of knowledge around leptin as a potential treatment for AD since dysfunctions in the leptin system have recently been linked to neurodegenerative disorders such as Alzheimer's disease." (PMID 22536534, 2012). "Case in point is the recent report of a curious association between increased plasma levels of the adipokine leptin, a molecule that regulates appetite, and a lower risk of incident dementia and Alzheimer disease (AD)." (PMID 20672007, 2010). "Recent studies have also linked alterations in the circulating levels of leptin to Alzheimer’s disease, where patients with this disorder have lower than normal levels." (PMID 17618127, 2007). "These attributes of leptin in the brain confer protection against the risk of Alzheimer's disease." (PMID 35185745, 2021). "Furthermore, the TA input is an early target for neurodegeneration in Alzheimer’s disease (AD) and aberrant leptin function is linked to AD." (PMID 28819795, 2019).
Alzheimer disease (continued). "Two metabolically active compounds produced by fat cells, leptin and adiponectin, are involved in this inverse relationship, and these compounds could play a role in the Alzheimer’s disease cancer risk pattern in DS as well." (PMID 29587359, 2018). "Reduction of abnormal levels of leptin and adiponectin could reduce the risk of childhood leukemia and Alzheimer’s disease." (PMID 29587359, 2018). "Alzheimer’s Disease risk later in DS could rise as weight increases, leptin levels fall and leptin’s neuroprotective actions diminish." (PMID 29587359, 2018). "In addition, dysfunctions in the leptin system have recently been linked to neurodegenerative disorders such as Alzheimer's disease." (PMID 22254146, 2012). "In addition, recent studies have linked dysfunctions in the leptin system with the development of neurodegenerative disorders such as Alzheimer's disease." (PMID 22254146, 2012). "Interestingly, the serum concentration of leptin shows an inverse relationship with the risk of Alzheimer's disease in later life." (PMID 21464984, 2011). "In fact, it has been established that the effects of leptin-based therapeutic strategies are potentially useful for patients with diverse diseases, besides congenital metabolic leptin deficiency disorders, such as mood disorders, Alzheimer’s disease and autism." (PMID 30185147, 2018). "In contrast to the pro-Alzheimer’s disease effects of increased adiponectin levels, physiologic adiponectin levels reduced beta-amyloid toxicity in human neuroblastoma cells, suggesting a dose-response relationship and the possible importance of the leptin/adiponectin ratio in pathogenic processes." (PMID 29587359, 2018). "Finally, in broader human disease, dysfunctions in the LEP system have recently been linked to neurodegenerative disorders such as Alzheimer’s disease, and therefore, LEP has been suggested as a novel therapeutic target in Alzheimer's disease." (PMID 23921638, 2013). "This deranged hippocampal leptin signaling can very well be a contributing factor to neuronal degeneration, linking metabolic dysfunction directly to cognitive decline in Alzheimer’s disease." (PMID 39594988, 2024). "Our findings reinforce the emerging consensus that the leptin system is a promising biomarker for tracking or monitoring cognitive decline and potential therapeutic target in Alzheimer’s disease and cognitive decline." (PMID 38684691, 2024). "In patients with Alzheimer’s disease, leptin signaling in the hippocampus is decreased and leptin localization is shifted, being more abundant in reactive astrocytes and less reactive in neurons." (PMID 39594988, 2024). "It is also involved in neurogenesis and neuroprotection, and central leptin resistance is related to some neurological disorders, e.g., Parkinson’s and Alzheimer’s diseases." (PMID 36674935, 2023). "Patients with Alzheimer’s disease, compared to healthy people, are characterized by significantly higher levels of leptin, cystatin C and tau protein, and lower levels of neuropilin-1." (PMID 37959320, 2023). "Leptin has also been shown to have neuroprotective effects against the progression of Alzheimer’s Disease (AD) pathology." (PMID 35527735, 2022). "In the researches of neurological diseases such as Parkinson's disease, Alzheimer's disease and multiple sclerosis, it is found that leptin shows neuroprotective properties." (PMID 36456983, 2022). "Several studies have suggested that greater adiposity in older adults is associated with a lower risk of Alzheimer’s disease (AD) related cognitive decline, some investigators have postulated that this association may be due to the protective effects of the adipose tissue-derived hormone leptin." (PMID 36570534, 2022). "With regards to neurodegenerative diseases, leptin can affect them via neuroprotection, mainly including Alzheimer’s disease and Parkinson’s disease." (PMID 31130833, 2019).